BPIFB2 (BPI fold containing family B member 2)
Synonyms: BPIL1; C20orf184; LPLUNC2; dJ726C3.2; RYSR
Tractability: Antibody: its Gene Ontology location is reachable by antibodies, with high confidence; UniProt places it where antibodies can reach, with medium confidence; UniProt predicts a signal peptide or a membrane-spanning region.
Gene: Protein-coding gene on chromosome 20 (33,007,704 to 33,023,709, forward strand). Ensembl gene ENSG00000078898.
Subcellular location: Secreted
Subcellular location (Human Protein Atlas): Vesicles; Predicted to be secreted
Pathways (Reactome):
Metabolism of proteins: Post-translational protein phosphorylation; Regulation of Insulin-like Growth Factor (IGF) transport and uptake by Insulin-like Growth Factor Binding Proteins (IGFBPs)
Immune System: Antimicrobial peptides
Gene Ontology:
Molecular function: lipid binding
Cellular component: extracellular exosome; endoplasmic reticulum lumen; extracellular region
Genetic constraint (gnomAD): Loss-of-function variants: 38 observed, 51.93 expected, observed/expected ratio (o/e) 0.73, 90% interval 0.56 to 0.96. The upper end of that interval is the gene's LOEUF score, 0.96, which puts it in group 4 of 6, group 1 being the genes least tolerant of losing a copy. Missense variants: 574 observed, 598.7 expected, observed/expected ratio (o/e) 0.96, 90% interval 0.89 to 1.03. Synonymous variants: 280 observed, 258.95 expected, observed/expected ratio (o/e) 1.08, 90% interval 0.98 to 1.19.
Homologues: Orthologues: chimpanzee BPIFB2 (99% identical), macaque BPIFB2 (96% identical), dog BPIFB2 (78% identical), rabbit BPIFB2 (74% identical), guinea pig BPIFB2 (72% identical), rat Bpifb2 (69% identical), mouse Bpifb2 (68% identical), pig BPIFB2 (68% identical), tropical clawed frog bpifb2 (27% identical), Caenorhabditis elegans C06E8.5 (14% identical). Paralogues in human: BPIFB3 (26% identical), BPIFB4 (25% identical), BPIFB6 (22% identical), BPIFC (20% identical), BPI (18% identical), LBP (18% identical), PLTP (17% identical), BPIFB1 (16% identical), CETP (15% identical), BPIFA1 (7% identical), BPIFA2 (7% identical), BPIFA3 (7% identical).
Diseases named in the same sentence as BPIFB2 in open-access papers:
BPIFB2 is named in the same sentence as 10 diseases in open-access papers, as found by Europe PMC text mining. Sharing a sentence is not in itself a finding about the gene and the disease. The quoted sentences say what the papers report.
acute pneumonia (1 paper, 2021). "Previous studies have shown that BPIFB2 is a distinct marker of inflammation; high levels of BPI proteins are released by different pathogens during acute pneumonia; BPIFB2 is also associated with ORF3 regulation in Hepatitis E virus- (HEV-) mediated hepatitis." (PMID 34315133, 2021).
nasal polyps (1 paper, 2021). "Similarly, other studies have also reported profound decreases in the expression of BPIFA1 and BPIFB2 in nasal polyps and LTF in nasal tissue of CRSwNP patients." (PMID 33506054, 2021).
cancer (4 papers, 2019 to 2022). A tumor composed of atypical neoplastic, often pleomorphic cells that invade other tissues. "BPIFB2 was involved with PD-L1 expression and PD-1 checkpoint pathway in cancer and immune-cell modulation." (PMID 32226313, 2020). "AZGP1, BPIFB2 and KLK1 were significantly downregulated in our data of which role of KLK1 and AZGP1 is well reported in cancer but BPIFB2 remains unexplored." (PMID 33564003, 2021).
bacterial infection (1 paper, 2022). "The BPIFB6, BPIFB4, BPIFB2, and BPIFB3 genes are the most significant because they are involved in biological signaling pathways, which play an essential role in innate immunity against bacterial infection." (PMID 36672756, 2022). "The BPIFB6, BPIFB4, BPIFB2, and BPIFB3 genes were the most significant because they are involved in biological signaling pathways, which play an essential role in innate immunity against bacterial infection." (PMID 36672756, 2022).
tumours (1 paper, 2021). "Statistically significant downregulation of BPIFB2 was observed in the early stage OSCC (both primary tumour stage and regional lymph node metastasis)." (PMID 33564003, 2021). "For KLK1 ROC curve was significant for all conditions except N+ cases and for BPIFB2 curve was significant for all conditions except N+ cases and late stage of primary tumour cases (T3/T4)." (PMID 33564003, 2021).
BPIFB2 also shares sentences with these, for which no sentence is quoted: allergic rhinitis (1 paper); chronic rhinosinusitis (1); gastric cancer (1); Hepatitis (1); lung adenocarcinoma (1).